NRK (Nik related kinase)
Description:
May phosphorylate cofilin-1 and induce actin polymerization through this process, during the late stages of embryogenesis. Involved in the TNF-induced signaling pathway (By similarity).
Synonyms: DKFZp686A17109; NESK
Tractability: Small molecule: it belongs to a druggable protein family.
Gene: Protein-coding gene on chromosome X (105,822,394 to 105,958,611, forward strand). Ensembl gene ENSG00000123572.
Subcellular location (Human Protein Atlas): Cytosol; Nucleoplasm
Gene Ontology:
Molecular function: protein kinase activity; ATP binding; protein serine kinase activity; protein serine/threonine kinase activity
Biological process: positive regulation of JNK cascade
Homologues: Orthologues: chimpanzee NRK (96% identical), macaque NRK (93% identical), dog NRK (85% identical), pig NRK (81% identical), rabbit NRK (79% identical), rat Nrk (65% identical), mouse Nrk (65% identical). Paralogues in human: TNIK (31% identical), MAP4K4 (30% identical), MINK1 (29% identical), SLK (13% identical), MAP4K3 (13% identical), TAOK1 (13% identical), STK10 (12% identical), MAP4K5 (12% identical), MAP4K2 (12% identical), TAOK3 (12% identical), MAP4K1 (11% identical), TAOK2 (11% identical), and 23 more.
Diseases named in the same sentence as NRK in open-access papers:
NRK is named in the same sentence as 23 diseases in open-access papers, as found by Europe PMC text mining. Sharing a sentence is not in itself a finding about the gene and the disease. The quoted sentences say what the papers report.
Hypertension (2 papers, 2024 to 2025). The presence of chronic increased pressure in the systemic arterial system. "NOS3 (fetal and maternal-acting), NRK (fetal), and ADAMTS8 (maternal-acting) have been implicated in placental function and hypertension." (PMID 39809772, 2025). "NOS3, NRK, and ADAMTS8 (fetal and maternal-acting) have been implicated in both placental function and hypertension." (PMID 38633783, 2024).
autism spectrum disorder (1 paper, 2017). A spectrum of developmental disorders that includes autism, and Asperger syndrome. "Previous studies did not denote any association between NRK and schizophrenia; however, an important paralog of this gene is TAOK2, which is essential for dendrite morphogenesis and has been associated with autism spectrum disorder." (PMID 28195569, 2017).
breast carcinoma (1 paper, 2020). "In breast cancer (BRCA), overexpression of six dark kinases is associated with decreased overall survival (ALPK3, CSNK1A1L, CSNK2A3, NRK, POMK, and PSKH1)." (PMID 33205077, 2020).
breast tumors (1 paper, 2019). "In addition, we have found that Nrk mutant female mice develop breast tumors frequently, suggesting that NRK is a tumor-suppressor gene." (PMID 31783915, 2019).
chordoma (1 paper, 2025). Chordomas are rare malignant tumors arising from embryonic remnants of the notochord in axial skeleton. "The expression analysis identified significant downregulation of SPOCK3, NRK, MYH8, DLK1 and SLN, alongside upregulation of HLA-DQA1, GDA, CXCL11, CXCL9 and ADAMDEC1 in chordomas." (PMID 40386066, 2025).
dilated cardiomyopathy (1 paper, 2024). Cardiomyopathy which is characterized by dilation and contractile dysfunction of the left and right ventricles. "Notably, Benzoylaconine emerges as a potential candidate for treating Dilated Cardiomyopathy, potentially exerting its therapeutic effects by targeted modulation of myocardial energy metabolism through NRK and NT5." (PMID 38510644, 2024).
energy metabolism disorders (1 paper, 2024). "Benzoylaconine holds promise as a therapeutic drug for addressing energy metabolism disorders in DCM with HF by targeting NRK and NT5E." (PMID 38510644, 2024).
heart failure (1 paper, 2023). Inability of the heart to pump blood at an adequate rate to meet tissue metabolic requirements. "In addition, three target genes (ITIH5, NRK, PDE5A) in DCM and RGS4 in heart failure have been reported to be up-regulated, the expression trend of these genes is consistent with our analysis results." (PMID 37268658, 2023).
hypermobility syndrome (1 paper, 2017). "NRK is a protein-coding gene, which is associated with hypermobility syndrome, hyperinsulinemic and hypoglycemia." (PMID 28195569, 2017).
hyperplastic (1 paper, 2024). "Our novel data identified NRK was upregulated in hyperplastic prostate and associated with prostatic stromal cell proliferation, apoptosis, cell cycle, migration, fibrosis and EMT process." (PMID 38459501, 2024). "Collectively, this is the first study to reveal both NRK gene and protein expression increased in hyperplastic prostate, while knockdown of NRK inhibited prostatic stromal cell proliferation and cycle, promoted cell apoptosis." (PMID 38459501, 2024). "The current study aims to identify differentially expressed genes (DEGs) in hyperplastic prostate and to explore the role of Nik related kinase (NRK) in BPH." (PMID 38459501, 2024).
ischemic cardiomyopathy (1 paper, 2025). Ischemic cardiomyopathy is a cardiomyopathy in which a weakness in the muscle of the heart due to inadequate oxygen delivery to the myocardium with coronary artery disease being the most common cause. "Bulk RNA-seq data from the GSE116250 cohort revealed significant overlap between ischemic cardiomyopathy (ICM)-associated differentially expressed genes (DEGs) and FB3-specific markers (THBS4, NTM, NRK, COL14 A1 upregulated; MGST1 downregulated)." (PMID 40447667, 2025).
lung adenocarcinoma (1 paper, 2025). A carcinoma that arises from the lung and is characterized by the presence of malignant glandular epithelial cells. "Similarly, NRK emerged as a poorly characterized but highly phosphorylated kinase in HCC-827 lung adenocarcinoma cells, suggesting a subtype-specific dependency." (PMID 41035678, 2025). "NRK protein and phosphorylation levels were markedly elevated in a subset of cell lines, particularly HCC-827 (lung adenocarcinoma)." (PMID 41035678, 2025).
psoriasis (1 paper, 2019). An autoimmune condition characterized by red, well-delineated plaques with silvery scales that are usually on the extensor surfaces and scalp. "We observed the upregulation of CMKLR-1, COL8A-1, NETO-2, NRK, SYTL-2, and SULF-2 in dermal mesenchymal stem cells derived from patients with psoriasis at both mRNA and protein level, however, a significant downregulation of SFRP-2 between two groups." (PMID 30760317, 2019). "We observed significant increases in protein expression of CMKLR-1, COL8A-1, NRK, and SYTL-2 in DMSCs from patients with psoriasis compared with those from healthy donors, whereas the expression level of SFRP-2 was obviously decreased." (PMID 30760317, 2019). "In the present study, the downregulation of SFRP2 and overexpression of CMKLR, COL8A, NRK, and SYTL2 reported herein revealed enhanced migratory and invasive potential abilities from DMSCs to other cells in psoriasis, which may be beneficial to the immunomodulatory properties of MSCs." (PMID 30760317, 2019).
renal carcinoma (1 paper, 2024). A carcinoma arising from the epithelium of the renal parenchyma or the renal pelvis. "Rapamycin also reduced PRAS40 in kidney cells HK2 and NRK, and renal cancer cell 786–0." (PMID 39333852, 2024).
renal fibrosis (1 paper, 2024). A final common manifestation of a wide variety of chronic kidney diseases characterized by glomerulosclerosis and tubulointerstitial fibrosis. "Since mitochondrial damage has been acknowledged as a primary factor responsible for renal fibrosis 25-27, we tested the mitochondrial function of NRK-49F in the absence of glutamine." (PMID 38250160, 2024).
tumor (4 papers, 2016 to 2025). "While direct studies in OC are more limited to SERP2 and NRK, their upregulation in this context suggests a possible role in inflammation-related signaling and tumor-stroma interaction, consistent with the inflammatory enrichment observed in our KEGG analysis." (PMID 40427104, 2025). "In the past, NAMPT inhibitors (NAMPTi) showed modest anti-tumor activity mostly because NAMPT block was bypassed by compensation through other NAD-biosynthetic pathways, such as that regulated through NAPRT and NRK." (PMID 33419372, 2020). "In the case of the tumor cells used for this study, NAMPT and NRK seem to play a major role in NAD+ biosynthesis, as the simultaneous inhibition of NAMPT and CD73 significantly decreased intracellular NMN and NAD+ concentration." (PMID 26658104, 2016).
cancer (3 papers, 2014 to 2020). A tumor composed of atypical neoplastic, often pleomorphic cells that invade other tissues. "Three of these non-synonymous mutations modified known cancer genes (MSN, NRK, GPR112)." (PMID 25175524, 2014). "Several studies have already revealed that IDO1 expression in a large number of cancers could lead to the depletion of TRP and accumulation of NRK and KYN, which inactivates T effector cells and thus suppresses immunity." (PMID 31805976, 2019).
infection (3 papers, 2016 to 2023). The state of being infected such as from the introduction of a foreign agent such as serum, vaccine, antigenic substance or organism. "An increase in ERK1/2 phosphorylation in both NRK and HL-1 cells was observed during the host cell infection." (PMID 36897926, 2023). "Both cell types underwent infection with the lentiviral constructs, with the efficiency (as judged by GFP expression) higher in NRK than in Melan-a cells." (PMID 27841340, 2016).
NRK also shares sentences with these, for which no sentence is quoted: benign prostatic hyperplasia (1 paper); cervical cancer (1); Hypoglycemia (1); lung carcinoma (1); schizophrenia (1).